IL10 (interleukin 10)
Diseases named in the same sentence as IL10 in open-access papers (continued):
Sharing a sentence is not in itself a finding about the gene and the disease.
infection (continued). "In vitro infection of Siglec-10 overexpressing cells resulted in increased IL-10 expression in a p38-dependent manner." (PMID 24823621, 2014). "IL-10 is a pleiotropic anti-inflammatory cytokine that is produced by immune cells and indirectly regulates cellular recruitment to the site of infection." (PMID 24632804, 2014). "SbR-LD infection enhances IL-10 production indicating its importance in observed immune suppression." (PMID 25032977, 2014). "In infected animals, all cytokine protein levels analyzed, except for IL-10, were increased 12 hours after infection as compared to uninfected mice, independently of genotype." (PMID 25033194, 2014). "In this study, the expression profiles of the studied cytokines in terms of fold change (IFN-γ > IL-4 > IL-12p40 > TNF-α ≥ IL-10) were consistent with those demonstrated in previous studies of early infection when foetal death prevailed." (PMID 24479988, 2014). "Our results indicate that IL-6, IL-8, and MCP-1 were much more potent than IL-10 in promoting death due to a secondary infection." (PMID 24886652, 2014). "Infection models have produced unequivocal evidence that IL-10 is responsible for pathogen persistence and thus, neutralization of IL-10 resulted in more effective clearance of Leishmania from the splenic compartment." (PMID 24428931, 2014). "The anti-inflammatory cytokine IL-10 was induced in higher levels than the mock with serovar Ba infection secreting significant amounts compared to mock." (PMID 25123797, 2014). "We infected IL-10-GFP mice with LCMV Cl13 or Arm and monitored GFP/IL-10 expression in total splenocytes following infection." (PMID 24613988, 2014). "Infection with the Cj1316 mutant showed a similar reduction in IL-10 secretion comparable to the flaA mutant (P < .001)." (PMID 24823621, 2014). "Very low levels of parasite-specific IL-10 were detected after the stimulation of spleen cells derived from vaccinated mice, 10 weeks after infection." (PMID 25333662, 2014). "When mice were given both ST and S.b-B, we observed the up-regulation of IFN-γ and the down-regulation of IL-10 in the early phase of infection (0–90 min) along the small intestine, even in the portion containing very small loads of bacteria." (PMID 25118595, 2014). "Next we did the same suppression assay performed earlier by isolating iTreg from KD-SbR-LD infection and addition of neutralizing IL-10 alone abolished the suppressive activity compared to that of iTreg from wild type SbR-LD-PBMC." (PMID 25032977, 2014). "IFNγ and IL-10 cytokines were measured in liver and spleen tissue homogenates, as well as in serum samples at 15 weeks post-infection, by ELISA." (PMID 25108307, 2014). "We blocked the CCR5 and TLR2 receptor by CCR5 specific siRNA and Cobra peptide respectively and evaluated the production of IL-10 during infection." (PMID 24695099, 2014). "Anti-inflammatory cytokine IL-10 plays an important role in the suppression of infection-induced inflammatory events because of its pleiotropic effects in immunoregulation." (PMID 24894878, 2014). "Due to these facts, a limited involvement of PGE2 and IL-10 on glial responses to infection can be supposed." (PMID 25386119, 2014). "For example, the severe infection group had higher levels of IL-10 than the silent infection group during the AP." (PMID 24646014, 2014). "IL-10 neutralizing antibody significantly abrogated the CCR5 expression in macrophages during the course of H37Rv infection." (PMID 24695099, 2014). "In mice with an established infection, the IL-10 mRNA acquires more stability and IL-10 secretion by NK is enhanced." (PMID 24966857, 2014). "High levels of IL-10 were detected in the end of immunization schedule and also after the infection with cercariae." (PMID 25144756, 2014). "We also observed remarkable increases in IL-1β, IL-2, IL-10 and TNF-α at 7 dpi after which IL-1β and IL-2 dropped to pre-infection levels, IL-10 and TNF-α decreased to lower levels than pre-infection levels." (PMID 24465897, 2014).
infection (continued). "We measured concentrations of TNF-α, IFN-γ, MCP-1, IL-6, IL-10 and IL-12p70 in plasma of Asc−/−, Nlrp3−/− and WT mice 2 and 5 days after infection." (PMID 25115174, 2014). "Amongst the B-cell populations analyzed, the precursor MZ-like B-cells were the main expressors of IL-10 during the early phase of infection in both the rapid and classic progressor groups." (PMID 25003989, 2014). "In rainbow trout, we also observed an up-regulation of IL-10 transcription after 5 days of infection suggesting a certain degree of regulation in trout liver responses." (PMID 25338079, 2014). "Vaccinated pigs also showed a more efficient shut-off of the TNF-α, IL-6, and IL-10 responses in the late phase of natural infection." (PMID 26664910, 2014). "In order to evaluate the role of antiviral innate immunity following SHIVSF162P4cy infection, the production of cytokines (IL-10, IFNγ, IL-15) and α-defensins were determined in plasma of infected monkeys." (PMID 24695530, 2014). "C. jejuni 11168H WT infection led to approximately 2-fold increase in IL-10 secretion from Siglec-10 RAW264.7 transduced cells, compared to infection in GFP control-transduced cells (P < .01)." (PMID 24823621, 2014). "Three cytokines (IL-6, IFN-γ, IL-10) increased significantly in the early stage of infection, but they all decreased to control levels at the late stage." (PMID 24666970, 2014). "Consistently with our results, other authors also observed an up-regulation of TGFβ and/or IL10 after the infection of bovine MDMs with live Map that down-regulated the production of TNFα." (PMID 25111300, 2014). "Both IFN-γ and IL-10 significantly increased at day 6 post-infection, but all rapidly decreased to the control level later on." (PMID 24666970, 2014). "For the infection group, mean IL-1β and IL-10 concentrations in PBMC culture media were significantly lower than for the control group." (PMID 25252649, 2014). "Plasma levels of α-defensins, IL-10 and IFNγ peaked in the acute phase of infection, whereas IL-15 showed fluctuation throughout the study (data not shown)." (PMID 24695530, 2014). "It would be of a major interest to determine the immune effector cells targeted by S.b-B that are responsible for the production of IFN-γ and IL10 which induce a protective effect against ST infection." (PMID 25118595, 2014). "Although a high IFN-γ:IL-4 ratio (1.34) was observed demonstrating Th1 bias, a low IFN-γ:IL-10 ratio (0.6) was found to correlate with the exacerbation of infection in spleen observed following L. donovani challenge." (PMID 24428931, 2014). "The majority of the deaths occurred during the acute phase of the infection when the host immune response peaks and before additional protective mechanisms like IL-10 or the IL-13 decoy receptor (IL-13Rα2) are fully activated." (PMID 25211233, 2014). "Understanding the mechanism (s) by which MAP enhances macrophage secretion of IL-10 will provide insight into the immune evasion strategies that contribute to a persistent infection." (PMID 24885748, 2014). "Here, we have shown the increased production of IFN-γ and decreased production of IL-4 and IL-10 in spleen cells after seven days of infection that indicates the systemic Th1 polarization induced by LaSP-Ex intranasal vaccination." (PMID 25239157, 2014). "By contrast a lack of IFN-γ, induction of FoxP3+ T cells and increased IL-1β and IL-10 secretion were indicative of progressive infection in Sham vaccinated animals." (PMID 25480162, 2014). "In parallel, cellular responses such as DC- and T cell-derived cytokine production (e.g. IL-1β, IL-8, TNF-α, IL-12, IFN-γ, IL-10) are modulated during early and late phases of infection both peripherally and locally in primary/secondary lymphoid organs." (PMID 24735253, 2014).
infection (continued). "Our study provides insight into the seemingly disparate findings as to which cell types are key producers of IL-10 in vivo, and how infection of DCs contributes to both the IL-10 production loop and T cell exhaustion in chronic viral infection." (PMID 24613988, 2014). "Although IL-10 is considered a major mediator that facilitates the infection, it is also able to prevent inflammatory injuries due to exacerbated Th1 immunity." (PMID 24743161, 2014). "Higher level of TGF-β from acid neutralized SbR-supernatant and higher expression of surface bound TGF-β in iTreg isolated from SbS-LD-PBMC proves the association of IL-10 and TGF-β in the iTreg mediated immune suppression in SbR-LD infection." (PMID 25032977, 2014). "A similar IL10-dependent functional impairment of CD4+ T cells has been described in other infections such as HIV that are characterized by chronic high-level antigen stimulation." (PMID 24415936, 2014). "In contrast, a significant reduction (P < 0.01) of ~3.8 folds (IL-1ß), ~3.97 folds (TNFa) and ~4.9 folds (IL-10) was seen in depolymerase + gentamicin treated group on peak day of infection (day 3)." (PMID 25149315, 2014). "In an experimental model, IL-10 expression is elevated in M. leprae-infected IFN-γ knockout mice which exhibit less resistance to infection compared to control mice." (PMID 25210773, 2014). "In the chronic LCMV infection model, both elevated IL-10 and enhanced infection of dendritic cells (DCs) are important for viral persistence." (PMID 24613988, 2014). "IL-10, a cytokine with anti-inflammatory properties, plays a central role in infection that involves limiting the immune response to pathogens and thereby preventing damage to the host." (PMID 24478702, 2014). "These small genomic changes translate to discreet differences in viral tropism (enhanced infection of DCs and fibroblastic reticular cells) and subversion of the immune response (elevated IL-10 expression and early T cell exhaustion)." (PMID 24613988, 2014). "IL-10 plays a crucial role for the down-regulation of MHC-II expression in antigen presenting cells during the course of various infections." (PMID 24695099, 2014). "GFP/IL-10 expression was readily detected as early as 2 days post-infection (dpi) in Cl13-infected mice, and by 15 dpi we observed a ten-fold increase (over naïve reporter mice) in the proportion of cells expressing IL-10." (PMID 24613988, 2014). "Newborn cord plasma IL-10 concentrations are higher in newborns than in adults, both at baseline and after infection." (PMID 25309541, 2014). "Studies of oral MA infection have reported low levels of pro-inflammatory cytokines and instead a local and systemic IL-10 response induced during infection." (PMID 24572168, 2014). "Urinary IL-6 was positively correlated to and IL-10 was negatively correlated to infection intensity and urinary tract inflammation in S. haematobium-infected children." (PMID 25223302, 2014). "The analyses showed that during the acute phase of infection IL-10 production was related to plasma viral load (p = 0.0023), and a significant relationship was also detected between α-defensins and viral RNA at the peak of viral load (p = 0.0286)." (PMID 24695530, 2014). "But interestingly the percentage of CD4+CD25+CD127low/− iTreg cells increases at late time point in SbR-LD infection and these cells also contributes to IL-10 production considerably." (PMID 25032977, 2014). "Other authors indicate that Treg cells can produce IL-10 induced by their IL-10R in a feed-forward loop and also, in certain infection contexts, they can express the T-bet transcription factor and produce IFN-y, without losing their suppressive ability." (PMID 24846008, 2014). "Triggering of macrophages by TLR2- or TLR4-activating bacteria impacts IL-10 secretion by these cells, suggesting a potential relevance of the described mechanism for modulating the course of the immune response during infection." (PMID 24227629, 2014).
infection (continued). "T regulatory cells (or TRegs) are important in maintaining gut homeostasis and regulating the response to infection of the chicken and other species through production of cytokines such as IL-10 and tumor growth factor beta (TGF-β)." (PMID 24987092, 2014). "This is the first report suggesting a positive feedback loop exists for the dual regulation of CCR5 and IL-10 during the course of infection." (PMID 24695099, 2014). "At different times after infection, the infection indices, cytokine production (IL-12p40 and IL-10), NO release and arginase activities were evaluated." (PMID 25376381, 2014). "Both beneficial and deleterious effects of elevated IL-10 in neonatal mice were noted upon infection with group B Streptococcus (GBS)." (PMID 25309541, 2014). "Previous infection was associated with an accentuated immune response characterized by a significant production of IFN-γ, IL-5 and IL-10." (PMID 24401094, 2014). "During the acute phase of infection, IL-10 correlated positively with viral load and negatively with CD4+T cell counts." (PMID 24695530, 2014). "Collectively these data point to enhanced infection of DCs as a key trigger of the IL-10 induction cascade resulting in maintenance of elevated IL-10 expression in CD4 T cells and inhibition of LCMV-specific CD4 and CD8 T cell proliferation." (PMID 24613988, 2014). "rCPA and rCPB immunizations although showed heightened IFN-γ and IL-12 expression, also enhanced expression of disease promoting cytokines like IL-4 and IL-10 mRNAs after infection, which perhaps limited their vaccine efficacy." (PMID 25144181, 2014). "The infection induced a significant increase of IL-4 and IL-10 in serum and the culture of splenocytes, whereas, OVA induced a significant increase of IL-17A in serum and splenocyte supernatants compared with in the PBS control mice." (PMID 25409540, 2014). "In THP-1 cells C. jejuni 11168H WT infection led to an increase in IL-10 secretion from Siglec-10 transduced cells compared to GFP control-transduced cells (P < .001)." (PMID 24823621, 2014). "Specifically, at both days 3 and 6 post-infection, IFNG, IL6, TNF, MIP1B and IL10 were all significantly diminished in MYD88-deficient mice as compared to wild-type mice." (PMID 25192715, 2014). "BMDC infected with BCG-GFP secreted low levels of IL-10 (50 to 100 pg/ml, similar to that reported earlier following infection of 5 day cultured C57BL/6 with the Erdman strain of MTB), which was completely extinguished by BCG-TB1860." (PMID 24945624, 2014). "Th1 type cytokines (IFN-γ, TNF-α) are involved in immune activation and then the injury of HBV antigen expressed hepatocytes, while Th2 type cytokine productions (IL-10, IL-4) inhibit immune reaction and involved in the persistence of infection." (PMID 25144199, 2014). "Infected neonatal mice had significantly elevated IL-4 and IL-10 production compared to infected adults 28 days post infection (P = 0.0248, 0.0434 respectively)." (PMID 24376704, 2013). "In a neonatal mouse model, neonatal mice overproduce IL-10 during infection, which is known to trigger a detrimental effect." (PMID 23737810, 2013). "In SIV-infected rhesus macaques, IL-10 production in lymph nodes is already detected at day 7 and increases further by day 28 post-infection." (PMID 23383108, 2013). "Regarding TGF-β1 secretion, we observed augmented production of this cytokine in IL-10 KO spleen cells at 2, 3, and 6 weeks post-infection compared to wild-type animals." (PMID 24069337, 2013). "To this end, we performed intracellular cytokine staining for IFN-γ of lymph node cells of the different IL-10 mutant mouse strains 7 days after infection with L. major." (PMID 23825956, 2013). "The dominant IL-10 producing cell population varies with different infections, likely reflecting differences in pathogen-specific responses and tissue-specific immune regulation." (PMID 24244162, 2013).
infection (continued). "Compared to WT mice, lower numbers of CD4+CD25+FoxP3+ Treg cells were detected in lungs of IL-10−/− mice at the 16th week post-infection." (PMID 24205424, 2013). "The infection of CD1b+ L-DCs with Salmonella for 6h induced a significant increase in IL-1ß, IL-6, IL-12p40 and IL-10 mRNA, whereas only IL-6 mRNA increased after Hc-ES stimulation." (PMID 24223964, 2013). "Rather, they underscore our findings demonstrating that IL-10−/− mice are able to resolve an infection with P. brasiliensis." (PMID 24205424, 2013). "Increased expression of IFNγ, IL-10, and FOXP3 has been associated with longer episodes of infection." (PMID 23457650, 2013). "S. aureus-induced IL-10 production was also found in the livers and blood of WT mice at 6 h post-infection, and continued to increase through 5 d post-infection." (PMID 24058538, 2013). "Here, we show that the persistent intracellular pathogen Brucella abortus prevents immune activation of macrophages by inducing CD4+CD25+ T cells to produce the anti-inflammatory cytokine interleukin-10 (IL-10) early during infection." (PMID 23818855, 2013). "Compared to Wt mice, immunosuppressive IL10 was elevated in Ifnar1−/− 72 h after i.g. infection, but reduced after i.p. infection." (PMID 23840314, 2013). "IL-10−/− mice were shown to have similar bacterial loads in the lung and enhanced levels of IFNγ production during early infection compared to wild type control mice, though the elevated IFNγ failed to provide any additional protection." (PMID 24350246, 2013). "We are currently developing methods to analyze the cells within leishmanial lesions from patients, which will allow us to identify the IL-10 producing cells that are important in controlling immune mediated pathology at the infection site." (PMID 23555256, 2013). "Although IFN-γ, IL-10, and TNF-α responses remained intact in the MLN and spleen late during infection of CXCR3-deficient mice, a significant decrease in IL-12 production was observed in the MLN and spleen of Cxcr3−/− mice." (PMID 24130498, 2013). "Taking mock-infected fish as a reference, expression of several cytokines (IFN-γ2, IL-1β, IL-6, and IL-10) was up-regulated as early as day 3 post-infection." (PMID 23865540, 2013). "However, two weeks after infection, despite comparable footpad swelling, the T cell-specific and the complete IL-10-deficient mice displayed markedly reduced parasite loads within the draining lymph nodes, compared to the macrophage/neutrophil-specific IL-10 mutant and the Cre− control mice." (PMID 23825956, 2013). "In late stages of infection, we observed higher amounts of cytokines in lung homogenates from WT mice, as compared to IL-10−/− mice, except for IL-2." (PMID 24205424, 2013). "Differing genetic backgrounds of the IL-10−/− mice and differences between mouse models and human infection make these data difficult to interpret." (PMID 23869227, 2013). "Commercially available ELISA assays were used to quantify IL-8 and IL-10 secretion during infection." (PMID 24223777, 2013). "A cytokine secretion assay 7 days after infection with L. major revealed only a very small number of IL-10-secreting CD4+ cells in the draining lymph nodes." (PMID 23825956, 2013). "In contrast, in other infections such as with K. pneumoniae, experimental inhibition of IL-10 signalling restores pathogen control and reduces the severity of disease." (PMID 23554169, 2013). "In this study, analysis from C. trachomatis infected macrophages revealed increased levels of GM-CSF, IL-1α, IL-1β, IL-6, TNF, IL-12p70, and IL-10 after a 2-day infection, with TNF, IL-6, and IL-1α being more robustly produced." (PMID 23766556, 2013). "DCs induce production of numerous cytokines including TNFα, IL-6, IL-10, and IL-12 upon infection with Mtb in vitro." (PMID 24350246, 2013).